CD4 (CD4 molecule)
Diseases named in the same sentence as CD4 in open-access papers (continued):
Sharing a sentence is not in itself a finding about the gene and the disease.
infection (continued). "Both the CD4 and CD8 counts after breakthrough infection were significantly lower than those before infection, whereas the CD4/CD8 ratio remained similar between the groups." (PMID 38140668, 2023). "One month post-infection, both CD4 + and CD8 + S-specific memory T cells (Median: 0.021% and 0.012%, respectively) were detected." (PMID 37974069, 2023). "Splenic IAV-specific CD4 T cells were also activated by the re-infection, increasing their expression of CD69 and ICOS, although the expression of Ifnγ was equivalent to that in memory animals." (PMID 37842651, 2023). "In contrast, the number of IFN-γ+CD4+ T cells responding to T4 was significantly higher in mice with coinfection compared to T4 single infection." (PMID 37222516, 2023). "Despite their importance, our understanding of CD4 T cell distribution in virus-targeted CNS tissues, their response to infection, and potential recovery following initiation of ART remain limited." (PMID 38060615, 2023). "Yet another complexity in assessing the latent viral reservoir are the inherent differences between CD4+ T and myeloid cells in their carrying capacities and transcriptional machineries that support infections." (PMID 37513726, 2023). "Under conditions of chronic infection, in which CD8+ T cells take several months or more to clear the infection, CD4+ T cells play an important role in maintaining CD8+ T cell activity." (PMID 38203441, 2023). "Repeated injections of CD4+ T cells during four weeks after infection and transduction with IFN-β decreased HIV viral load, suggesting a potential infection eradication." (PMID 36680271, 2023). "We had to incorporate this measure of virulence, because CD4+ T cell levels after primary infection varied significantly between subtypes and this counteracted the disease predictions based solely on the decline of CD4+ T cells." (PMID 37161335, 2023). "We focused on the assessment of C. burnetii-induced intracellular cytokine production by monocytes and CD4 T cells, effector cells that are known to promote killing of C. burnetii and clearance of infection." (PMID 37885896, 2023). "The spontaneous clearance of RHV in mice depends on the presence of CD4 T cells during the early days of infection." (PMID 37812637, 2023). "We observed that the frequency of CD4+FoxP3+ bTreg cells was initially low during the acute phase of infection (i.e., day 7 post prime-CNS boost), but this fraction increased within the brain by day 30 post prime-CNS boost." (PMID 37192971, 2023). "The heterogeneous basal infection level was broad among the patients, and the mean of change of p24 released by the CD4+ T cells after NaMiX stimulation was very large." (PMID 37936122, 2023). "Several groups have also attempted to mimic infection in activated CD4+ T cells by collecting and isolating CD4+ T cells from people without HIV (PWoH) and activating the cells." (PMID 37513726, 2023). "HIV-1 invades the body and preferentially attacks activated CD4+ T cells, most of which die rapidly after infection, whereas a small proportion, called latent cells, tend to enter a resting state and stay dormant for a long time." (PMID 37608956, 2023). "Overall, the data show that there is an increase in CD4 T cells expressing PD-1 within the brain parenchyma and CNS during the chronic phase of infection, even with suppressive ART." (PMID 38060615, 2023). "One important finding of our study showed incongruence between the definition of LPs based on CD4 counts and on the recentness of infection (based on sequence ambiguity rates)." (PMID 38140659, 2023). "The median rate of CD4 T cell decline per month amongst 14 ART naïve FRESH participants (following acute infection to 12 moths post infection) calculated by linear regression was −15.90 cells/mm3 (IQR, −27.42 to -2.67)." (PMID 37307292, 2023).
infection (continued). "Paniskaki and colleagues found that alpha variant–reactive CD4+ and CD8+ T-cell responses were very poor at disease onset in patients with moderate-to-critical breakthrough infection compared with uninfected vaccinated controls." (PMID 37033936, 2023). "An immune CD8+ T-cell activation is observed in convalescent patients, irrespectively of developing PASC in which the CD4/CD8 ratio remain low upon six months of infection." (PMID 36997530, 2023). "And we have demonstrated that γδ T cells and CD4+CD8+ DP T cells significantly increased at the early stage after infection and displayed differential activation and differentiation." (PMID 36960295, 2023). "The numbers of Ifnγ+ T cells peaked at day 10 post-infection with similar numbers of cytokine+ CD4 and CD8 T cells." (PMID 37842651, 2023). "We found several lines of evidence suggesting that antigen specificity is an important determinant of CD4 T cell activation at the site of infection." (PMID 38110410, 2023). "Activated CD4+ T lymphocytes can activate macrophages, and then produce cytokines that are recruited to the infection site." (PMID 37122740, 2023). "Rather, inhibition of IL‐27 during the initial 7 days of infection was critical, suggesting that IL‐27 inhibits the generation of memory precursor CD4+ T cells that were destined toward differentiation to Th1‐type." (PMID 37855243, 2023). "Innate lymphoid cells (ILCs) predominantly produce IL-22 during the early stages of infection through an IL-23-dependent pathway, whereas CD4+ T cells secrete IL-22 during the later stages of infection via an IL-6-dependent pathway." (PMID 37646028, 2023). "This has been established on the basis of a newly defined measure of virulence—the rate of disease progression—which combines both the decline of CD4+ T cells and the CD4+ T cell level after primary infection." (PMID 37161335, 2023). "To do so, we followed the same procedure as with productive infection: PHA-activated CD4 + T cells were cultured alone or co-cultured with IEC on day 6 post-activation, and on day 7 post-activation, they were infected with the GFP reporter virus." (PMID 37202790, 2023). "CD4+ T-cell levels <300/μL in the blood can be used as threshold for the clinical prediction of early infection." (PMID 37360336, 2023). "Unlike mucosal sites in the respiratory tract, ongoing viral replication in this model occurs primarily in the SGs, facilitated by the induction of CD4+ T cells that produce IL-10, which peak on day 14 post-infection (p.i.)." (PMID 37440306, 2023). "Further research is required to determine more specific criteria that delineate the TCF1+ progenitor-like CD4+ T-cell subset in our infection model, as other populations of CD4+ T cells express both TCF1 and CXCR5." (PMID 37691941, 2023). "Taken together, these data suggest that the SVR generates a higher frequency of infection resistant CD4+ T cells than do the other two regimens." (PMID 37153584, 2023). "In this context, it will be interesting to also evaluate the possible role of CD4+ T cells in mediating such a partial vaccine-induced protection against lethal IAV challenge infection." (PMID 37513714, 2023). "For influenza, pre-existing CD4 and CD8 T cell responses have been associated with lower rates of infection, suggestive of T-cell mediated-aborted infections." (PMID 36901802, 2023). "In contrast, in MFD-fed infected mice, both F4/80+ and CD4+ cells significantly infiltrated the lungs during both acute and chronic stages of infection compared to uninfected mice." (PMID 36676177, 2023). "Previous study showed that knockout of YTHDF3 in human CD4+ T-cells increases infection supporting the role of YTHDF3 as a restriction factor." (PMID 37726690, 2023). "In a separate line of work, we have established that appropriate densities of antigen presentation by B cells during the contraction phase of an infection, induces quiescence in antigen experienced CD4 T cells, as they differentiate into memory T cells." (PMID 37908352, 2023).
infection (continued). "These include memory subsets with highly potent functions such as T follicular helpers and cytotoxic CD4 effectors at sites of infection, where they can most effectively combat the pathogen early after re-infection." (PMID 38152398, 2023). "Patients with infectious events had lower CD3+ T cells (540 vs. 994 cells/μL, p = 0.05) and lower CD4+ T cells (161 vs. 605 cells/μL, p = 0.0029), when compared to infection-free patients in the same time interval." (PMID 37515152, 2023). "These were immediate ART initiation if eligible; functional status at enrollment; WHO stage at enrollment; duration of infection since known; and baseline CD4 of index cases of HIV." (PMID 36780456, 2023). "A significant increase in the number of CD4 cells at the intestinal level was recorded after infection with viral hemorrhagic septicemia virus in rainbow trout." (PMID 37370408, 2023). "We found that previous infection induced CD4 T cells that vigorously responded to pools of peptides derived from the S and N proteins." (PMID 37313411, 2023). "We found low frequencies of Foxp3+CD4+ Tregs at 8 dpi, which only slightly increased during the course of infection in the bone marrow." (PMID 37427590, 2023). "The models for multivariable logistic regression involving the CD4+ T-cell levels and other influencing factors had good applicability and effectiveness in evaluating early infection." (PMID 37360336, 2023). "Helper T cells are CD4+ T lymphocytes that stimulate other immune cells to respond to infection and when activated, Adora2b receptor levels increase on the CD4+ T cell surface." (PMID 37187740, 2023). "HIV-1 infected cells were also shown to secrete Nef-loaded exosomes, which depleted CD4 levels, confirming the complexity of the roles of exosomes in infection as they can be employed both as hijacked viral agents and as part of host innate defense mechanisms." (PMID 37376186, 2023). "This provides a platform for systematically altering the composition of cellular memory to detect discrete effects of cell subsets and enables more precise studies of CD4+ memory T cells generated following infection or vaccination." (PMID 36346178, 2023). "Studies on HIV infection have shown how the metabolic activity of a cell plays an essential role in virus susceptibility, where CD4+ T cells with high glycolysis and OXPHOS have a higher permissiveness to infection." (PMID 36695947, 2023). "Parameter sensitivity and viral dynamics simulations show that even when the infection of CD4+ T cells is completely blocked by therapy, the virus can still persist, and the steady-state viral load is not sensitive to the change in treatment efficacy." (PMID 37476291, 2023). "On the 14 days post-infection, the effector CD4+ T cells (CD3+CD4+CD44hiCD62Llo) were sorted from lungs and ex vivo stimulated with recombinant IL-25 or IL-33 or the combination of IL-25 and IL-33." (PMID 37337050, 2023). "As the infection progresses, infiltrating CD4+ and CD8+ T cells are recruited to the site of infection producing type II IFN (IFNγ), as well as sentinel CD4+ and CD8+ resident memory T cells (TRMs) (12, –, 17)." (PMID 37655893, 2023). "In primary infection, strong SARS-CoV-2 specific CD4+ and CD8+ T cell responses are associated with reduced disease severity." (PMID 37655880, 2023). "Cellular immunity is also a crucial component of adaptive immunity for reducing disease severity and controlling pathogen infection, which involves both CD4+ and CD8+ T‐cell responses." (PMID 37125241, 2023). "Five weeks later, after recovery from infection, mice were treated with tamoxifen and further 3 weeks later, CD4+ T cells from spleen, mLN and colon were analyzed." (PMID 37469513, 2023). "Together, our findings provide a single-cell atlas of human antigen-specific CD4+ T cell responses following vaccination and infection and demonstrate unique properties of these antigen-specific cells in dLN and blood." (PMID 37790414, 2023).
infection (continued). "While infection at day 7 increased the CD8+:CD4+ T cell ratio in the lungs of both genotypes, this was significantly lower in TLR7 KO mice." (PMID 37795093, 2023). "These repeated results identifiedTnfrsf4/OX40 as a potentially useful marker gene for activated, parenchymal effector CD4 T cells at the site of infection." (PMID 38110410, 2023). "In the context of fugal pathogens, the main mechanisms involved in the immune response against infection are phagocytosis and the activation of the adaptive immune response via the development of different CD4+ T helper and regulatory T cells." (PMID 37367569, 2023). "The types of CD4+ T cell subsets and tissue origins of infections have only limited influences on HIV-1 integration." (PMID 36742330, 2023). "Our data show that the immune response induced either by natural infection with the Wuhan variant and/or vaccination generates SARS-CoV-2-specific antibodies and CD4+ T cells that cross-react with the VOIs/VOCs Gamma, Mu, and Delta." (PMID 37575243, 2023). "A study of patients with HIV has shown that a compromised CD4+ cell count leads to higher risks of developing a severe mpox infection." (PMID 37631913, 2023). "This study demonstrated that CD4 and CD8 T- cell responses were involved in the acute infection of ML29, and infection with ML29 itself possibly induced hearing loss." (PMID 36992218, 2023). "Here, we studied the effects of SARS-CoV-2 breakthrough infection on clinical characteristics, CD4 counts, HIV reservoir size, and T-cell immune recovery in a cohort of PLWH after booster vaccination, followed by a 2-dose inactivated vaccine." (PMID 38140668, 2023). "MDC has been shown to inhibit the replication of CCR5-dependent HIV in macrophages and play a protective role over CD4+ T cells from infection by HIV." (PMID 37731491, 2023). "Any reasonable measure of virulence therefore needs to take the level of CD4+ T cells after primary infection into account if there is variation in this level." (PMID 37161335, 2023). "This includes the impact of drugs on productive infection, the role of CD4 and endocytosis and the induction of NEIs." (PMID 37563144, 2023). "Strikingly, 90% of the cases were found to be in the middle to late stages of infection based on CD4+ T cell counts." (PMID 38314093, 2023). "This is therefore indicating that the infection is not only reducing the number of CD4+ and CD8+ T cells responding to the mitogen ConA, but that it is also limiting the production of IFN-γ in the responding cells." (PMID 37920474, 2023). "Compared with phosphate-buffered saline (PBS)-treated mice, IL-17RB+ CD4+ T cells were gradually increased within the lung during C. neoformans H99 infection and significantly induced at 7 and 14 days post-infection." (PMID 37337050, 2023). "Recent studies suggest that tissue-resident memory T cells (Trm) play an important role in the primary defense against infection and that Mtb-specific CD4 and CD8 T cells with tissue-resident memory phenotypes are associated with protection." (PMID 36845108, 2023). "Further verification with CD4+ T cells isolated from healthy human peripheral blood showed that the mRNA and protein levels of HSPA14 in the CD4+ T cells infected with HIV-1 pseudoviral particles also decreased with increasing infection time." (PMID 36845091, 2023). "CD4 T cells activated by infection were detected in the blood by flow cytometry using antibodies to BrdU and CD11a, which has been shown to be upregulated in response to antigen, but not cytokines." (PMID 36920200, 2023). "Numbers of CD8+ and CD4+ T-lymphocytes were significantly increased 1 mo after infection with Lm 10403s." (PMID 37143648, 2023). "As a result of infection, these CD4+ T lymphocytes (e.g., Mtb-specific T lymphocytes) are destroyed by apoptosis, contributing to the breakdown of granuloma integrity, a decrease in Mtb control, and an increase in the bacterial load." (PMID 37110276, 2023).
infection (continued). "SL15649 infection resulted in a significant increase in CD4+ T cells within the corpus callosum, while AF15561 infection caused a significant increase in CD8+ T cells compared to mock PBS-infected controls." (PMID 37243143, 2023). "We measured the SERINC5 down-regulation activity of 106 subtype C Nef clones, isolated from individuals in early infection, for which the Nef activities of CD4 and HLA-I down-regulation as well as alteration of TCR signalling were previously measured." (PMID 37004071, 2023). "Although OX40 contributes to CD8 T cell protection in mouse infection models with some viruses and Listeria26–30, we found that it is predominantly expressed by CD4 T cells and rarely by CD8 T cells in the lungs after Mtb infection." (PMID 38110410, 2023). "Functionally activated CD4+Tcm subsets were increased by 30.8%–393% after challenge infection in pregnant mice, with the higher extent of CD4+Tcm subsets stimulation being observed in infected (vs. vaccinated/infected) pregnant mice (p < 0.05–0.01)." (PMID 38104118, 2023). "ODC-1 expression analysis in various tonsillar CD4+ subsets showed the least expression of the protein in TregDys in a non-infection setting." (PMID 36693889, 2023). "Decreased production of IL-21 and IL-4 has been reported with human ageing, impairing memory CD4+ T cell responses to infection and vaccination efficacy." (PMID 37106796, 2023). "Of note, despite having an active infection and higher levels of systemic immune activation compared with HIVfree individuals, CD4+ T cells from EC donor expressed low levels of TLR7, insufficient to promote IRF-5 and cell death." (PMID 37227774, 2023). "Of all R5-tropic infections, the baseline CD4+ T cell count (p < 0.0001, p < 0.0001) and baseline CD4+ T/CD8+ T ratio (p < 0.0001, p = 0.0075) were lower in CRF01_AE compared to CRF07_BC and CRF08_BC." (PMID 37152735, 2023). "On DPI 7, there was also a decrease of the CD4/CD8 ratio in infected animals compared to the ratio before infection, indicating an increase of the CD8+ subset compared to the CD4+ subset." (PMID 37243138, 2023). "The immunity of CD4+ T cell subsets against human cytomegalovirus (HCMV) is considerable due to their essential role in controlling the infection in transplant individuals." (PMID 37403036, 2023). "Latent infection can be reactivated via CD4 + T cell activation such as through PMA/Ionomycin stimulation." (PMID 37202790, 2023). "At the endpoint, which was seven days after infection, the spleens were harvested and analyzed for three populations: CD4+, CD8+, and CAR T cells." (PMID 37513726, 2023). "Since CD4 memory T cells are generated after infection and vaccination, they are considered beneficial to mount a faster antibody response upon reinfection." (PMID 37313411, 2023). "HIV interacts with several recently discovered cellular receptors in addition to the cluster of differentiation 4 (CD4) protein on cell surfaces during the stages of infection and HIV enters the cell upon virus-cell fusion." (PMID 37288215, 2023). "More recently, in C57BL/6 germfree mouse, parasite multiplication was higher than in normal NMRI mice due to a lower number of CD4 + T cells producing cytokines interferon-γ (IFN-γ) controlling the infection." (PMID 37773515, 2023). "Following infection, DCs capture and present pathogen antigens to naive CD4+ T cells in secondary lymphoid tissues." (PMID 37917177, 2023). "We found that FIV establishes a latent infection in peripheral CD4 T cells and an active infection in circulating monocytes." (PMID 37632117, 2023). "Just as was the case for X4-tropic virus, IEC stimulation also increased infection with R5-tropic virus in activated and memory CD4 + T cells." (PMID 37202790, 2023). "Rora reporter mice received a primary N. brasiliensis infection, followed by a secondary infection 35 d after the first infection, to further investigate Rora-expressing CD4+ cells in the lungs." (PMID 37387671, 2023).